BRCA1 (BRCA1 DNA repair associated)
Diseases named in the same sentence as BRCA1 in open-access papers (continued):
Sharing a sentence is not in itself a finding about the gene and the disease.
breast cancer (continued). "Therefore, assessment of presence or absence of mentioned haplotype in the BRCA1 microsatellites can be used for prognosis in individuals, suspected of having or not having breast cancer." (PMID 27351029, 2016). "Moreover, the implementation of PARP inhibitors faces considerable limitations in that not all BRCA1/2 breast cancer patients have shown a response to PARP inhibition and resistance can occur, emphasizing the need for new therapeutic alternatives." (PMID 26610585, 2015). "The biological background of BRCA1/2 and different pathological aspects of BRCA1-associated tumours support the hypothesis that patients carrying a BRCA1 and/or BRCA2 mutation might have a worse breast cancer prognosis compared to non-carriers." (PMID 25816289, 2015). "The efficacies and specificity for NHE1 inhibition of these compounds and their potential for use in future clinical and/or pre-clinical trials should be considered for the treatment of triple-negative breast cancer, as well as for BRCA1-positive breast cancer." (PMID 25514463, 2015). "Therefore, in this study, patients suffering from cancer were employed as the priority group, as these patients have an increased chance of having a BRCA1 gene alteration than healthy females without breast cancer." (PMID 25624909, 2015). "In breast cancer, several critical genes reportedly undergo aberrant hypermethylation, including genes involved in cell cycle regulation (p16, Cyclin D2), cell apoptosis (DAPK), DNA repair (BRCA1), cell adhesion (CDH1) and cell signal transduction (ER and RARβ2)." (PMID 26451736, 2015). "However, many women with a family history of breast cancer, including many who carry BRCA1 or BRCA2 mutations, never develop breast cancer." (PMID 26538066, 2015). "In the Breast Cancer Prevention Trial, healthy women with a BRCA2 mutation receiving tamoxifen had a reduction of breast cancer by 62 %, an effect not seen among those with a BRCA1 mutation, but the overall number of individuals was very small." (PMID 26669313, 2015). "Tamoxifen appears to be effective in reducing breast cancer in carriers of BRCA2 but not in carriers of BRCA1.17,18 The differential effect of tamoxifen may be due to the differential expression of the estrogen receptor in tumors of BRCA carriers." (PMID 26886774, 2015). "On the basis of these results, we evaluated PARP inhibitors as single-agent therapy in 14 breast cancer cell lines: 4 BRCA mutant lines with BRCA1 allelic loss, 9 BRCA wild-type lines with BRCA1 allelic loss, and 1 BRCA wild-type line without BRCA1 allelic loss." (PMID 25975349, 2015). "However, our findings indicate that decreased BECN1 (but not decreased BRCA1) expression characterizes breast cancers that have aggressive molecular and clinical characteristics." (PMID 25825707, 2015). "To evaluate the status of the inactive X chromosome in different types of breast cancer, we selected three cell lines that represent the main breast cancer molecular subtypes: ZR-75-1 (luminal), SK-BR-3 (HER2+), and MDA-MB-436 (Basal-Like Carcinoma [BLC], BRCA1 null)." (PMID 25653311, 2015). "The association we observed among BRCA2, but not BRCA1, mutation carriers may reveal a functional alteration that would be specific to mechanisms involving BRCA2-related breast cancer." (PMID 25925750, 2015). "Moreover, BRCA1-related breast cancer is associated with a basal-like phenotype in which EGFR is a basal marker and approximately one in five BRCA1 mutated breast cancers which were negative for ER and PR expressed AR." (PMID 25695063, 2015).
breast cancer (continued). "If this experimental finding holds in pre-clinical or clinical studies, many more breast cancer patients could benefit from PARP inhibitor therapy, because HR repair is deficient in many cancers without BRCA1 or BRCA2 mutations." (PMID 25769025, 2015). "BRCA1 expression was lacking in 60.4% of the breast cancer patients." (PMID 25051360, 2014). "Luciferase reporters with the BRCA1-3’UTR-variant (T allele) displayed significantly lower gene expression, as well as altered response to external hormonal stimuli, compared to the non-variant 3’UTR (G allele) in breast cancer cell lines." (PMID 24915755, 2014). "However, mammosphere cultures derived from BRCA1-silenced MCF7 or MDA-MB-231 breast cancer cells (enriched in ALDH1 expression) were no longer sensitive to the growth inhibitory effects of vitamin D3." (PMID 25460500, 2014). "However, the v.4.2013 of these guidelines indicated that individuals with breast cancer by 35 years of age, not before 30 years of age as in previous version, and negative for BRCA1/2 fulfills LFS testing criteria." (PMID 24625245, 2014). "Ubc9 binding site mutations, as well as disease associated mutation in the BRCA1 RING domain (C61G), disrupted the ability to regulate Ubc9-mediated estrogen-induced ER-α transcriptional activity in breast cancer cells but did not disrupt SUMO-1 binding nor auto ubiquitination activity of BRCA1." (PMID 25594072, 2014). "Consistent with breast cancer stem-cell data, Western blot analysis revealed an inverse relationship between ALDH1A1 and BRCA1 expression in A2780/CP70 cells, suggesting ALDH1A1 expressing ovarian cancer stem-like cells more likely to lose or express low levels of BRCA1." (PMID 25216266, 2014). "Furthermore, BRCA1 mutation carriers seem to predominantly develop estrogen and progesterone receptor-negative and HER2-negative (triple-negative) breast cancer." (PMID 24959366, 2014). "While there is significant correlation between BRCA1 mutation and development of breast cancer, it is still controversial whether or not there is a correlation between the presence of methylated BRCA1 promoter in WBC and paired tumor DNA from breast cancer patients." (PMID 25403427, 2014). "Premenopausal women with TNBC may be candidates for genetic testing for BRCA1/2 in the Xinjiang region of China, even in the absence of a family history or bilateral breast cancer." (PMID 24961674, 2014). "Because DSS1 maintains BRCA2 expression by regulating its ubiquitin-dependent degradation and because the BRCA1:BRCA2 imbalance promotes tumorigenesis by increasing genomic instability, we predicted that increased expression of DSS1 could suppress breast cancer development." (PMID 24289229, 2013). "Potentially, the signatures could also be used as a tool for preselecting patients for mutation screening, as a significant proportion of BRCA1 and BRCA2 germline mutation carriers do not have a family history of breast cancers." (PMID 23704984, 2013). "In this work, we showed that cucurbitacin B obviously inhibited knocked-down and mutant BRCA1 breast cancer cells rather than the wild type BRCA1 breast cancer cells in regards to the cellular proliferation, migration, invasion and anchorage-independent growth." (PMID 23393598, 2013). "BRCA1 is repressed in sporadic breast cancer in the absence of hypermethylation suggesting that it too could be repressed prior to hypermethylation." (PMID 23341493, 2013). "Furthermore, BRCA-1 and BRCA-2 germ line mutations account for only a quarter of the total breast cancer cases and a significant portion of women with breast cancer acquire the affliction in the absence of this familial link." (PMID 29147364, 2013). "In addition, not all breast cancer patients with BRCA1 mutations respond to PARP inhibitors and a substantial fraction of advanced BRCA1-mutant cancers are resistant to these agents." (PMID 23388117, 2013).
breast cancer (continued). "It is likely that not all ERα-negative breast cancers share dysfunctions in BRCA1 signalling and that intrinsic subgroups may show normal or indeed constitutively active Notch signalling." (PMID 23863842, 2013). "Recently, three BRIP1 missense mutations have been identified in high-risk Jewish women, who have been tested negative for mutations in BRCA1 and BRCA2 genes, indicating that BRIP1 mutations can contribute to breast cancer susceptibility in Jewish high-risk families." (PMID 23586058, 2013). "In contrast to Hollestelle and colleagues, who found increased frequency of the KRAS variant among cases from BRCA1 positive families, we did not observe an association between the KRAS variant and either cases from BRCA1, BRCA2 or non-BRCA breast cancer families." (PMID 22436609, 2012). "However, almost 70% of breast cancer families with four or more cases of early onset breast cancer under the age of 60 show no convincing evidence of linkage to BRCA1 or BRCA2." (PMID 22703186, 2012). "Moreover, in breast cancer cells, Id4 and the tumor suppressor BRCA1 exist in a negative feedback loop." (PMID 23342267, 2012). "In our study, almost 40% of BRCA1-positive breast cancers could be classified according to family history as not-familial." (PMID 22395474, 2012). "Given that breast cancers in germline BRCA1 carriers are predominantly estrogen-negative and triple-negative, it has been suggested that women diagnosed with triple-negative breast cancer (TNBC) younger than 50 years should be offered BRCA1 testing, regardless of family cancer characteristics." (PMID 23116406, 2012). "Furthermore, BRCA1 expression levels seem to predict breast cancer outcome in non-familial cases although data are not consistent." (PMID 22706632, 2012). "In addition, as the gene sensitive to cisplatin or other DNA damaging agents, expression of ERCC1 is closely related to BRCA1, no matter in breast cancer or in NSCLC." (PMID 22439756, 2012). "The role of gene fusions in BRCA1 breast cancers, however, has not been well explored." (PMID 22032724, 2011). "However, in the same study, ectopic expression of SIRT1 in BRCA1 wild type breast cancer cells did not inhibit tumour formation." (PMID 21698133, 2011). "The results presented here help explain how BRCA1 BRCT mutations might contribute to breast cancer through a mechanism involving increased, and most likely aberrant, HRR rather than through the loss of BRCA1 function and reduced HRR." (PMID 21666281, 2011). "Women who are BRCA1/2 mutation carriers and choose not to undergo prophylactic BSO may wish to consider the use of tamoxifen, as it has been shown to reduce breast cancer incidence in that group." (PMID 22295226, 2011). "The final version of the kit contained 34 target specific probes, corresponding to the BAC classifier regions, 7 reference probes, randomly spread over the genome and in regions not affected in breast cancer, 2 probes for BRCA1 and 2 probes for BRCA2, resulting in a total of 45 probes." (PMID 22032731, 2011).
breast cancer (continued). "To achieve a gene panel for developing a breast cancer blood-based test we quantitatively assessed the DNA methylation proportion of 248 CpG sites per sample (total of 31,248 sites in all analyzed samples) on 10 candidate genes (APC, BIN1, BMP6, BRCA1, CST6, ESR-b, GSTP1, P16, P21 and TIMP3)." (PMID 21283676, 2011). "Taken together, these data suggest that up-regulation of the expression of the tumour-suppressor genes (р53, BRCA1, SYK) and transcription factor E2F1 could be responsible for the antimitotic effect of D-glucuronyl C5-epimerase in human breast cancer cells in vitro." (PMID 20723247, 2010). "Not all of the breast cancer-associated SNPs assessed have been found to modify risk in carriers, however, and some of the risk associations are specific for BRCA2 mutation carriers only and not BRCA1." (PMID 21114847, 2010). "Our data showed that beclin 1 expression was significant higher in the BRCA1 positive tumors than in the negative ones, suggesting beclin 1 expression may be related to cell growth in breast cancer." (PMID 20230646, 2010). "The BRCA1 positive and negative status was a significant independent factor for improved OS (HR = 0.29; p = .002 and HR = 0.76; p = < .001, respectively) compared with the sporadic breast cancer cases." (PMID 20219108, 2010). "Indeed, a trend has been reported toward a higher percentage of lymph node negative, BRCA1-positive breast cancers as compared with controls." (PMID 20398395, 2010). "In addition, a lack of BRCA1 activates the AKT1 pathway by causing disappearance of the PTEN protein, which is observed in 82% of hereditary breast cancers linked to BRCA1." (PMID 21321378, 2010). "However, our recent results showed no mutation on BRCA-1 and one sample (1.5%) with unreported multiple mutations on BRCA-2 in 69 non-familial breast cancer samples." (PMID 24281079, 2010). "Further, WT-BRCA1, but not mutated BRCA1 increased the expression of Smad3 protein in a dose-dependent manner, while silencing of WT-BRCA1 by siRNA decreased Smad3 and Smad4 interaction induced by TGF-β in MCF-7 breast cancer cells." (PMID 19768112, 2009). "Although conventional Brca1 mouse models have enabled us to learn a lot about the biological functions of BRCA1, the observed embryonic lethality of homozygous animals and lack of mammary tumour development in heterozygous mice made it difficult to study the role of BRCA1 in tumour suppression." (PMID 19904273, 2009). "Similarly Wasieleski and colleagues have not noted a higher frequency of MDM2 309 SNP G/G in younger BRCA1/2 breast cancer patients." (PMID 19226467, 2009). "Because BRCA1 and BRCA2 expressions are often decreased, or even absent in sporadic breast cancer, abnormal BRCA1 or BRCA2 expressions may also play a role in nonhereditary tumors." (PMID 19442290, 2009). "In breast cancer cells, Id4 and BRCA1 are in a negative feedback loop." (PMID 19500415, 2009). "There is much need for markers that could be used to distinguish patients and families who are likely to carry a BRCA1/BRCA2 germline mutation from mutation-negative families and from breast cancer patients in general." (PMID 18275599, 2008). "We assessed if gene expression profiles could distinguish between BRCA1 or BRCA2 pathogenic truncating and missense mutation carriers and familial breast cancer cases whose disease was not attributable to BRCA1 or BRCA2 mutations (BRCAX cases)." (PMID 18497862, 2008). "Therefore, telomerase inhibition in the primary infiltrating ductal carcinoma cell line with a BRCA1 gene mutation, HCC1937, will be compared to a breast cancer cell line without detectible BRCA1 gene mutations, HCC1599." (PMID 18366791, 2008).
breast cancer (continued). "In a case–control study of 965 BRCA1 and 280 BRCA2 pairs, breast feeding did not influence breast cancer risk in BRCA2 carriers, but BRCA1 carriers who breast fed for over 1 year were less likely to have had breast cancer than those who never breast fed (OR=0.55, 95% CI 0.38–0.80)." (PMID 17213823, 2007). "However, a clinical study showed that locally advanced breast carcinomas negative for BRCA1 expression responded well to taxens, compared with those positive for BRCA1." (PMID 19690636, 2007). "Because BRCA1 and BRCA2 mutation carriers are susceptible to a much higher risk of breast cancer than non-carriers, the corresponding absolute differences in risk between parous and nulliparous carriers may be substantial." (PMID 17187672, 2006). "Using rigorously controlled semiquantitative RT–PCR and densitometry analysis, we found that a dose of I3C (60 μM) that causes little or no cytotoxicity caused a time-dependent increase in BRCA1 and BRCA2 mRNA levels in two breast cancer cell lines, MCF-7 and T47D." (PMID 16434996, 2006). "Presumably, this discrepancy results from the fact that BRCAPRO does not model any of the residual familial clustering of breast cancer, other than BRCA1 or BRCA2, so that individuals with moderate family histories are assigned probabilities for being mutation carriers that are too high." (PMID 16417652, 2006). "The prevalence of BRCA1 and BRCA2 mutations (approximately 1:500, but higher in Ashkenazi Jewish individuals) indicates that they are unlikely to account for more than 3% to 5% of all breast cancers." (PMID 16507150, 2006). "A potential criticism of our line of thinking could be that there is no haploinsufficient effect of a BRCA1 or BRCA2 mutation, and that anti-oestrogen treatment functions only as a secondary preventer of breast cancer." (PMID 16538216, 2006). "Furthermore, new data from Dr Narod's consortium suggest that tamoxifen does indeed prevent the development of breast cancers in BRCA1 carriers whose tumors are primarily negative (manuscript submitted; J. McClenann, personal communication)." (PMID 16457695, 2005). "Several studies have investigated the prevalence of BRCA1 and BRCA2 mutation in series of breast cancer cases unselected for FH in nonfounder populations (i.e. excluding populations such as the Ashkenazi Jewish or Icelandic populations where there are prevalent founder mutations)." (PMID 15381934, 2004). "Thus, contrary to BRCA1, large genomic rearrangements within the BRCA2 gene do not represent a major mutation mechanism among Dutch breast cancer families." (PMID 10638982, 2000). "The prevalence of germline BRCA2, and seemingly lack of BRCA1, mutations (5%) among Brunei breast cancer patients is similar to that of other Asian populations further highlighting the difference in BRCA genetics and associated breast cancer risk in Caucasian and Asian populations." (PMID 40531958, 2025). "The prevalence of BRCA1 and BRCA2 pathogenic variants in breast and other related cancers in various populations and clinical management guidelines of affected individuals were well established, and similar data of non-BRCA breast cancer susceptibility genes were also increasingly published." (PMID 38355628, 2024). "Interestingly, since the presence of BRCA1/2 mutations is the major cause of HRD, they used their ML model to predict the HRD status of 124 ovarian or breast cancers without mutations in any of the HR genes and 114 cancers with mutations in one of the genes involved in HR." (PMID 39220639, 2024). "One possible explanation is that the impact of PGS313 on OS may be confounded by other genetic risk factors, many of which have yet to be identified; several recent papers have found that PGS313 stratifies breast cancer risk in CHEK2, PALB2, and ATM carriers but not BRCA1/2 carriers." (PMID 38704641, 2024).